PRSS36 (serine protease 36)
Description:
Serine protease. Hydrolyzes the peptides N-t-Boc-Gln-Ala-Arg-AMC and N-t-Boc-Gln-Gly-Arg-AMC and, to a lesser extent, N-t-Boc-Ala-Phe-Lys-AMC and N-t-Boc-Val-Leu-Lys-AMC. Has a preference for substrates with an Arg instead of a Lys residue in position P1.
Synonyms: FLJ90661
Tractability: Antibody: UniProt places it where antibodies can reach, with high confidence; UniProt predicts a signal peptide or a membrane-spanning region; its Gene Ontology location is reachable by antibodies, with medium confidence.
Gene: Protein-coding gene on chromosome 16 (31,138,926 to 31,150,091, reverse strand). Ensembl gene ENSG00000178226.
Subcellular location: Secreted, extracellular space, extracellular matrix
Gene Ontology:
Molecular function: serine-type endopeptidase activity
Biological process: proteolysis
Cellular component: cytoplasm
Genetic constraint (gnomAD): Loss-of-function variants: 90 observed, 86.25 expected, observed/expected ratio (o/e) 1.04, 90% interval 0.88 to 1.24. The upper end of that interval is the gene's LOEUF score, 1.24, which puts it in group 5 of 6, group 1 being the genes least tolerant of losing a copy. Missense variants: 1,158 observed, 1,043 expected, observed/expected ratio (o/e) 1.11, 90% interval 1.06 to 1.16. Synonymous variants: 500 observed, 452.06 expected, observed/expected ratio (o/e) 1.11, 90% interval 1.03 to 1.19.
Homologues: Orthologues: chimpanzee PRSS36 (99% identical), macaque PRSS36 (96% identical), rabbit PRSS36 (86% identical), dog PRSS36 (85% identical), pig PRSS36 (85% identical), guinea pig PRSS36 (82% identical), mouse Prss36 (81% identical), rat Prss36 (79% identical), tropical clawed frog tpsb2 (13% identical), Drosophila melanogaster CG31954 (10% identical), Drosophila melanogaster CG8299 (10% identical), Drosophila melanogaster CG11192 (10% identical), and 26 more. Paralogues in human: PRSS53 (24% identical).
Diseases named in the same sentence as PRSS36 in open-access papers:
PRSS36 is named in the same sentence as 4 diseases in open-access papers, as found by Europe PMC text mining. Sharing a sentence is not in itself a finding about the gene and the disease. The quoted sentences say what the papers report.
Alzheimer disease (3 papers, 2021 to 2023). A progressive, neurodegenerative disease characterized by loss of function and death of nerve cells in several areas of the brain leading to loss of cognitive function such as memory and language. "PRSS36 encodes a serine protease, which has been associated with Alzheimer's disease by genome-wide association studies (GWAS) and by integrating GWAS and expression quantitative trait locus data." (PMID 36400229, 2023).
PRSS36 also shares sentences with these, for which no sentence is quoted: bipolar disorder (1 paper); depression (1); schizophrenia (1).